LBX1 (ladybird homeobox 1)
Description:
Transcription factor required for the development of GABAergic interneurons in the dorsal horn of the spinal cord and migration and further development of hypaxial muscle precursor cells for limb muscles, diaphragm and hypoglossal cord.
Synonyms: LBX1H; HPX6; CCHS3; HPX-6; homeobox
Tractability: No criterion of Open Targets' tractability assessment is met for any kind of drug.
Gene: Protein-coding gene on chromosome 10 (101,226,180 to 101,230,401, reverse strand). Ensembl gene ENSG00000138136.
Subcellular location: Nucleus
Subcellular location (Human Protein Atlas): Nucleoplasm; Cytosol; Nuclear bodies; Nucleoli
Gene Ontology:
Molecular function: protein binding; DNA-binding transcription factor activity, RNA polymerase II-specific; sequence-specific double-stranded DNA binding; DNA binding; DNA-binding transcription factor activity
Biological process: anatomical structure morphogenesis; regulation of transcription by RNA polymerase II; regulation of DNA-templated transcription
Cellular component: chromatin; nucleus; transcription regulator complex
Genetic constraint (gnomAD): Loss-of-function variants: 6 observed, 15.73 expected, observed/expected ratio (o/e) 0.38, 90% interval 0.21 to 0.75. The upper end of that interval is the gene's LOEUF score, 0.75, which puts it in group 3 of 6, group 1 being the genes least tolerant of losing a copy. Missense variants: 344 observed, 371.31 expected, observed/expected ratio (o/e) 0.93, 90% interval 0.85 to 1.01. Synonymous variants: 190 observed, 180.67 expected, observed/expected ratio (o/e) 1.05, 90% interval 0.93 to 1.19.
Homologues: Orthologues: chimpanzee LBX1 (99% identical), macaque LBX1 (99% identical), dog LBX1 (98% identical), pig LBX1 (98% identical), mouse Lbx1 (97% identical), rat Lbx1 (97% identical), guinea pig LBX1 (85% identical), rabbit LBX1 (83% identical), tropical clawed frog lbx1 (74% identical), zebrafish lbx1a (73% identical), zebrafish lbx1b (59% identical), Drosophila melanogaster lbe (37% identical), and 1 more. Paralogues in human: LBX2 (37% identical).
Diseases named in the same sentence as LBX1 in open-access papers:
LBX1 is named in the same sentence as 20 diseases in open-access papers, as found by Europe PMC text mining. Sharing a sentence is not in itself a finding about the gene and the disease. The quoted sentences say what the papers report.
adolescent idiopathic scoliosis (7 papers, 2013 to 2025). A scoliosis with no known cause arising in adolescent. "Previous studies have shown that LBX1 is associated with adolescent idiopathic scoliosis (AIS) in multiple populations." (PMID 34917617, 2021). "Previously, we identified an adolescent idiopathic scoliosis susceptibility locus near human ladybird homeobox 1 (LBX1) and FLJ41350 by a genome-wide association study." (PMID 26820155, 2016). "The results of studies investigating the association between the ladybird homeobox 1 (LBX1) gene polymorphisms and the risk of adolescent idiopathic scoliosis (AIS) are not all the same." (PMID 27450593, 2016).
scoliosis (7 papers, 2015 to 2023). A congenital or acquired spinal deformity characterized by lateral curvature of the spine. "Less is known about the specific functions of transcription factors NKX6-2 and LBX1 in bone metabolism, but mutations in the latter are associated with Scoliosis." (PMID 33929316, 2021). "Considering that rs11190870 could confer AIS susceptibility by activating LBX1 transcription, it would be reasonable to assume that upregulation of human LBX1 may contribute to some aspects of the pathogenic mechanism in scoliosis." (PMID 26820155, 2016). "LBX1 may be implicated in the aetiology of scoliosis through abnormal somatosensory function." (PMID 26394188, 2015). "In patients with severe IS, the deep paravertebral muscles demonstrate an asymmetric LBX1 promoter region methylation level, higher at the convex scoliosis side, which reveals the role of locally acting factors in IS progression." (PMID 36140724, 2022). "In patients with severe IS, the deep paravertebral muscles show an asymmetric LBX1 promoter region methylation level, higher at the convex scoliosis side, which reveals the role of locally acting factors in IS progression." (PMID 36140724, 2022). "Previous in vivo studies using Lbx1 knockout mice and lbx gene knockdown morphants in zebrafish or Xenopus did not reveal phenotypes associated with scoliosis." (PMID 26820155, 2016). "Thus, as a step towards better understanding of the genetic pathophysiology of scoliosis, our study provide a new evidence for a pathological role of LBX1 and its zebrafish homologs in body axis deformation." (PMID 26820155, 2016). "Thus, the current data do not support the possibility that loss-of-function of LBX1 is involved in susceptibility to scoliosis." (PMID 26820155, 2016). "Among the genes that have been confirmed to be involved in the development of scoliosis in humans (TBX6, FGF3, LBX1, POC5, TTLL1) and vertebrates (Kif6 and Ptk), several are ciliary genes." (PMID 37239471, 2023).
idiopathic scoliosis (6 papers, 2020 to 2025). A scoliosis with no known cause. "A SNP in the LBX1 gene has been associated with idiopathic scoliosis in humans, a disease that causes muscle atrophy." (PMID 40656592, 2025). "The present study thus suggests a potential association between LBX1 dysfunction and lean body mass in patients with adolescent idiopathic scoliosis." (PMID 39110747, 2024). "The LBX1 gene is located near a single nucleotide polymorphism that is highly associated with susceptibility to adolescent idiopathic scoliosis and is considered one of the strongest candidate genes involved in the pathogenesis of this condition." (PMID 39110747, 2024). "Genetic variation in the LBX1 locus has been associated with several human disease conditions, such as idiopathic scoliosis, congenital limb malformation, and neuropsychiatric illness, including attention-deficit/hyperactivity disorder (ADHD) and anxiety disorders." (PMID 41440000, 2025).
breast carcinoma (5 papers, 2012 to 2024). "For instance, KCNS1 and LBX1 are implicated in the metastasis of breast cancer." (PMID 38544827, 2024). "Although no further studies have been published so far regarding the role of LBX1 in breast cancer, its association with ER- and PR-negative cancers may hint at a regulation by steroid receptors." (PMID 26797644, 2016). "Another TF, LBX1 (Ladybird homeobox 1) can up-regulate the expression of ZEB1/2 and SNAIL1, promoting cell migration and invasiveness in breast cancer." (PMID 32318352, 2020). "We note that there was little correlation between TBX2 expression and E-cadherin status in established breast cancer cell lines, a finding, which has also been reported for the EMT-inducing transcription factor LBX1." (PMID 22844464, 2012). "LBX1 directly up-regulates ZEB1, ZEB2, Snail and TGFB2 but not Twist1 and promotes breast cancer cell migration, implying a role as a master regulator of EMT." (PMID 26797644, 2016).
Obesity (2 papers, 2017 to 2024). Accumulation of substantial excess body fat. "In conclusion, our data show that loss of LBX1 in skeletal muscle leads to resistance to obesity, improved glucose homeostasis, and increased energy metabolism, indicating that LBX1 functions as a negative regulator of energy metabolism." (PMID 39110747, 2024). "We found that loss of LBX1 rendered mice more resistant to high-fat diet-induced obesity, despite comparable food intake between mutant and control mice." (PMID 39110747, 2024). "Of note, our data indicate that loss of LBX1 has more pronounced effects in female than in male mice, particularly in glucose sensitivity and resistance to obesity." (PMID 39110747, 2024). "Even though no sufficient studies showed the association of two genes of KCNT1 and LBX1 with obesity, the results of functional annotation and enrichment analysis indicated that they were involved in intermediate-density lipoprotein particle and voltage-gated potassium channel complex, respectively." (PMID 29132311, 2017).
Anxiety (1 paper, 2025). Intense feelings of nervousness, tension, or panic often arise in response to interpersonal stresses. "In order to learn more about the mechanism how LBX1 could be linked to anxiety disorders, we extracted anxiety-related genes from several GWAS studies over the last few years and compared the gene lists with the regulated genes we found in the mutant line and the overexpression experiment." (PMID 41440000, 2025).
anxiety disorder (1 paper, 2025). A category of psychiatric disorders which are characterized by anxious feelings or fear often accompanied by physical symptoms associated with anxiety. "In a large meta-analysis of several GWAS using samples from patients with various anxiety disorders of European origin, a SNP in the LBX1 region was found to be associated with anxiety disorders using a factor score model." (PMID 41440000, 2025).
attention deficit-hyperactivity disorder (1 paper, 2025). A disorder characterized by a marked pattern of inattention and/or hyperactivity-impulsivity that is inconsistent with developmental level and clearly interferes with functioning in at least two settings (e.g. at home and at school). "Finally, whole-exome sequencing (WES) followed by targeted genotyping revealed that the minor A allele of the synonymous SNP rs941909 (G/A) located in exon 1 of LBX1 perfectly segregated with attention-deficit/hyperactivity disorder (ADHD) in an extended, high-density pedigree previously reported." (PMID 41440000, 2025).
colorectal cancer (1 paper, 2019). A primary or metastatic malignant neoplasm that affects the colon or rectum. "LBXCOR1 encodes a transcriptional corepressor of LBX1 and inhibits BMP signaling which predisposes colorectal cancers." (PMID 31699026, 2019).
glioma (1 paper, 2019). A benign or malignant brain and spinal cord tumor that arises from glial cells (astrocytes, oligodendrocytes, ependymal cells). "The genes RRM2, KIAA0101, UBE2C, LMX1A, DTL, and LBX1 demonstrated significant overexpression in all human glioma subtypes (GBM, ODG, OA, AA) with a p-value ≤ 0.0001." (PMID 31475119, 2019). "The remaining members of the top 10-upregulated genes, IRX5, KIAA0101, LBX1, and DTL, have been studied in other cancers, but have not been well-studied in glioma." (PMID 31475119, 2019).
lung carcinoma (1 paper, 2013). "However, not much has been studied and reported about LBX1 methylation and association in lung cancer." (PMID 24369052, 2013).
restless legs syndrome (1 paper, 2023). A condition that occurs while resting or lying in bed; it is characterized by an irresistible urgency to move the legs to obtain relief from a strange and uncomfortable sensation in the legs. "Mouse Skor1 is expressed in dI4 and dI5 spinal interneurons, where it binds Lbx1, and human Skor1 has been implicated in Restless legs syndrome (also known as Willis-Ekbom disease)." (PMID 38017520, 2023).
schizophrenia (1 paper, 2024). A major psychotic disorder characterized by abnormalities in the perception or expression of reality. "Indeed, polymorphisms at NHLH1 and LBX1 loci have been associated with schizophrenia and PD symptoms, respectively." (PMID 38177910, 2024).
respiratory disorder (1 paper, 2022). "More recently, the characterization of a CCHS disease-causing frameshift mutation in LBX1 has further revealed that this respiratory disorder originates from the misspecification of dB2 neurons in mice, and that this is caused by a lack of cooperativity between PHOX2B and LBX1." (PMID 36523603, 2022).
LBX1 also shares sentences with these, for which no sentence is quoted: cancer (2 papers); disc degeneration (2); asthma (1); endometriosis (1); prostate carcinoma (1); T-cell leukemia (1).